BARD1 (BRCA1 associated RING domain 1)
Diseases named in the same sentence as BARD1 in open-access papers (continued):
Sharing a sentence is not in itself a finding about the gene and the disease.
cancer (continued). "Furthermore, we found both the upregulated expression of BARD1δ and telomere aberrations in cells from cancer patients with germline mutations in BARD1 that predict expression of truncated FL BARD1 mRNAs." (PMID 28030839, 2017). "The cellular functions of BARD1 isoforms that are associated with cancer are still unclear." (PMID 28030839, 2017). "Loss of FL BARD1 was frequently found associated with expression of isoforms in many cancers." (PMID 28030839, 2017). "Moreover, full-length BARD1 and cancer-associated BARD1 mRNAs were downregulated by miR-203 and miR-101, and lncRNA BARD1 9′L counteracted the effect of these miRNAs." (PMID 25888444, 2015). "In spite of those findings, the functional role of BARD1 in cancer susceptibility is unclear." (PMID 23056176, 2012). "However, the association between P/LP BARD1 variants and an increased risk of other cancers, including colorectal cancer (CRC), remains unclear." (PMID 38485918, 2024). "Assuming that an oncogenic BARD1 splicing variant may render cancer cells more sensitive to HR inhibition, they showed how, in cell lines where there were higher levels of BARD1beta, which creates an unstable BARD1/BRCA complex, there was an increased sensibility to PARPi." (PMID 35326540, 2022). "Indeed, such studies investigating diverse populations worldwide support the hypothesis that potentially pathogenic variants in BARD1 confer a low–moderate risk to cancer, with perhaps a moderate risk to TNBC." (PMID 32726901, 2020). "We examined whether cancer-associated BRCT mutations affect the interaction of BARD1 with p50." (PMID 33024116, 2020). "Therefore, mutations affecting the BARD1/BRCA1 heterodimer structure may confer an increase in cancer risk." (PMID 27197561, 2016). "Emerging evidence highlights the role of post-transcriptional regulation in driving oncogenic BARD1 isoform expression across cancer types." (PMID 41009605, 2025). "Approximately 10% of patients with aggressive PC carry germline pathogenic variants in genes with established roles in cancer predisposition (BRCA2, ATM, CHEK2, NBN, BRCA1, PALB2, BRIP1, BARD1)." (PMID 41465280, 2025). "In cancer cells, mutations that disrupt these heterodimers can lead to the detrimental degradation of both BRCA1 and BARD1 proteins." (PMID 40805222, 2025). "Among other cancer susceptibility genes, associations were seen for ATM (p = 0.0013), BRCA1 (p = 0.0015), BARD1 (p = 0.00021), CHEK2 (p = 0.039), RAD51D (p = 0.0065), MSH3 (p = 0.0025)." (PMID 39749474, 2025). "Two CNVs (deletion of exons 4 to 11 and duplication of exons 1 to 9) in the BARD1 gene were also identified among non-cancer controls." (PMID 40805222, 2025). "Of these, 103 patients (8.6% of the total sample) carried germline pathogenic variants in genes that have been definitively linked to an increased risk of PC or other types of cancers (BRCA2, ATM, CHEK2, NBN, BRCA1, PALB2, BRIP1 and BARD1)." (PMID 41465280, 2025). "These isoforms are thought to have an oncogenic effect by interfering with the function of full-length BARD1 and are believed to contribute to tumorigenesis and cancer progression." (PMID 40805222, 2025). "To validate the binding of the genes with these four antibodies, we examined 8 candidate genes that are involved in cancer progression, including Esr1, Bcas3, and Bard1, as well as Crebbp, Myc, Rel, Gadd45g, and Shcbp1 (not shown)." (PMID 40157910, 2025). "Increased expression of OLA1 in cancer cells appears to enhance their survival by interacting with BRCA1 and BRCA1-associated RING domain proteins (BARD1)." (PMID 38889130, 2024).
cancer (continued). "Although BARD1 deletions have been reported in patients diagnosed with various cancers, including CRC, the germline deletion of BARD1 exon 3 represents a novel, previously unreported pathogenic variant." (PMID 38485918, 2024). "The single PPTP/C pediatric model (KT-10) with a homologous recombination deficiency (HRD) mirrors the clinical setting in which genetic loss of BRCA1/2, BARD1, PALB2, and other genes associated with HRD is uncommon in pediatric cancers." (PMID 39510293, 2024). "BRCA1 (breast cancer gene 1), BARD1 (BRCA1 associated RING domain 1) and MDM2 (mouse double minute 2 homolog) are well-known proteins containing this domain which play important roles in cancer progression." (PMID 39119040, 2024). "Four (8%) were identified with variants in cancer predisposition genes, including two with APC (mild increased risk), and one each with BARD1 and MUTYH; the latter of which was previously identified in the family." (PMID 38256266, 2024). "In recent decades, researchers have investigated the role of the BARD1 gene in cancer progression and its use as a prognostic biomarker and potential candidate for targeted cancer therapy." (PMID 37727789, 2023). "In the KEGG pathway enrichment analysis data demonstrated that; homologous recombination, ERBB signaling pathway, cell cycle, PI3K-Akt signaling pathway, microRNAs in cancer and pathways in cancer were associated with RAD21, RAD50 and BARD1." (PMID 37474724, 2023). "PARPi activity was also demonstrated for BRCAwt cancers due to mutations in genes critical for DNA repair (e.g., ATM, BARD1, BRIP1, CHEK2, NBN, PALB2, RAD51C, and RAD51D)." (PMID 36910637, 2023). "This is important since many studies have highlighted the role of these alternatively spliced isoforms of BARD1 in the tumorigenesis of other cancer types." (PMID 35406624, 2022). "For each patient, we also showed the risk in the well-known high-penetrance cancer risk alleles BRCA1 and BRCA2 with respect to other moderate-penetrance alleles including PALB2, CHEK2, ATM, BARD1, RAD51D, RAD51C and BRIP1." (PMID 35886069, 2022). "Among the interface genes in the Her2+_TNBC module, the known cancer-related genes are mostly DNA repair genes, such as BARD1, BRIP1, BRCA1, BRCA2, FANCA, FANCC, FANCD2, and FEN1." (PMID 35992864, 2022). "Nevertheless, additional studies and practical investigations are required to elaborate on the role of BARD1 in cancer and assist in generating strategies to guide the tract of the oncology field." (PMID 35650591, 2022). "In this study, we discussed plenteous reports that elucidated the dual roles of the BARD1 in cancer development." (PMID 35650591, 2022). "Upon Vorinostat treatment, an elevation of miR-19a and miR-19b levels was perceived that subsequently targeting BARD1 3’UTR expression enhancing the apoptotic activity of cancer cells." (PMID 35650591, 2022). "In various cancer types, differential expression of these BARD1 isoforms (α, β, γ, δ, and Φ) has been demonstrated to carry out a pro-tumorigenic role." (PMID 35406624, 2022). "Amongst these, ‘breast cancer 1, early onset (BRCA1)’; ‘BRCA1 associated RING domain 1 (BARD1)’; ‘BRCA1 interacting protein C-terminal helicase 1 (BRIP1)’; ‘H2A histone family, member X (H2AFX)’ and RAD51." (PMID 33491125, 2021). "BARD1 was localized in both the cytoplasm and nucleus in normal tissues; and, both compartments underwent distinct cancer-related changes." (PMID 34789768, 2021). "BARD1 alternatively spliced isoforms are abundant and some are highly expressed in different cancer types." (PMID 34824355, 2021). "Genes that are essential in eHAP cells include cancer risk genes such as PALB2, BARD1, RAD51C, and RAD51D, which have thousands of variants recorded in ClinVar." (PMID 33691754, 2021). "We also identified other deletions associated with higher HRD in multiple cancer types, such as XRCC2/3 and BARD1 deletion in BLCA, TP53BP1, and RAD51 deletion in OV and LUAD, and CHEK1 deletion in TCGT and SKCM, etc.." (PMID 34572800, 2021).
cancer (continued). "Looking back at the distribution of the BARD1 mutations in the HBOC family, we found that both of the surviving cancer patients shared alleles coding for two identical mutations: P24S and R378S." (PMID 33623049, 2021). "With the exception of one BARD1 variant, all of the rare variants in BARD1, MRE11, and NBN that were identified in FC cancer cases have also been reported in studies of BC and OC from other populations." (PMID 34298626, 2021). "In ovarian, breast, and other cancers, mRNA and protein isoforms of BARD1, generated by exon skipping, are overexpressed and correlated with tumour progression, while the full-length gene expression was abrogated." (PMID 34201956, 2021). "A truncated protein isoform of BARD1 was identified to provide immune protection from colon cancer in a murine cancer model." (PMID 34201956, 2021). "Our results elucidate how RNF19A-mediated ubiquitylation of BARD1 induces dissociation of BRCA1, unmasks the NES region of BARD1, restrains HR activity, and makes cancer cells more susceptible to PARPi treatment." (PMID 34789768, 2021). "Here we identify that RNF19A, a ring between ring fingers (RBR) family E3 ligase, interacts with and ubiquitinates BARD1, resulting in the nuclear export of BARD1, thus compromising HR and sensitizing cancer cells to PARPi." (PMID 34789768, 2021). "Nevertheless, FL BARD1 characterization is incomplete in cancer and major elucidation, related to mechanisms by which FL BARD1 results in potential oncogenic vulnerabilities, needs in the next years." (PMID 32047556, 2020). "Functionally, interaction with BARD1 promotes p50 protein stability and consistent with this, in human cancer specimens, low nuclear BARD1 protein strongly correlates with low nuclear p50." (PMID 33024116, 2020). "One patient with an unremarkable family history for cancer who developed a pancreaticoduodenal tumor with metastasis to the liver and abdominal lymph nodes was found to have a germline alteration in the BARD1 gene: c.69_70delins25 (p.Ala25Glyfs*41)." (PMID 32708251, 2020). "In this cancer, a highly significant positive correlation was seen between the amount of nuclear FL BARD1 and nuclear p50 protein (P = 6.14 × 10−8, Fisher’s exact test)." (PMID 33024116, 2020). "For instance, the dysfunction of BRCA1/2 and/or BARD1 sensitizes cancer cells to chromosomal instability and subsequent apoptosis induced by inhibition of poly (ADP‐ribose) polymerase (PARP) enzymatic activity." (PMID 32730698, 2020). "When expanding our investigation of other cancer predisposition genes besides ALK and PHOX2B, we detect rare variants such as a nonsense mutation in BARD1 as well as missense variants in CHEK2, BRCA2, and WRN." (PMID 33384420, 2020). "Altogether, these findings support the experimental manipulation studies and demonstrate that in clinical cancer specimens, the presence of low nuclear BARD1 is strongly correlated with low nuclear p50 protein." (PMID 33024116, 2020). "As BARD1 variants have also been identified in carriers of known cancer predisposing genes, BRCA1 and BRCA2, it will be important to explore if BARD1 variants modify risk in an epistatic or additive manner in this context." (PMID 32726901, 2020). "Germline variants in BARD1 and CHEK2 have indeed been shown to be enriched in NB patients, while BRCA2 has been shown to be enriched in pediatric cancer patients." (PMID 33384420, 2020). "Several cancer-derived mutations have been reported in the C-terminal region of BARD1, and this region is required for BRCA1/BARD1-mediated inhibition of MT aster formation." (PMID 32722046, 2020).
cancer (continued). "Further investigations are necessary to explore the role BARD1 function in cancer in the future as well as to determine the efficacy of PARPi in BARD1 mutated gene with its defective function." (PMID 30975222, 2019). "Since the discovery of BARD1 about 20 years ago, many studies have been carried out to try to understand its role in cancer." (PMID 31142030, 2019). "Multiple BARD1 mRNA isoforms of variable exon composition are expressed in human and murine cancers." (PMID 28030839, 2017). "This review is an overview of how BARD1 functions in tumorigenesis with opposite effects in various types of cancer." (PMID 29292755, 2017). "This is in line with what is observed in most cancers: the tumor suppressor FL BARD1 is down-regulated, while the expression of other splice isoforms is boosted." (PMID 28030839, 2017). "In recent years, truncated and deletion-bearing BARD1 isoforms, generated through alternative splicing of the BARD1 gene, have been discovered in various cancers and their expression correlated with disease progression and poor prognosis." (PMID 28786985, 2017). "Except for 3 pseudogenes (GUCY1B2, HNRNPA1P33, and TUBA3FP), all of the remaining 15 genes showed the most involvement as tumor suppressor genes in distinct carcinomas, and four genes (TUBGCP2, PLEC, CLEC11A, and BARD1) were associated with AML." (PMID 29299160, 2017). "This increased sensitivity to the PARPi, suggests therapeutic applications for cancer patients expressing this BARD1 isoform." (PMID 27197561, 2016). "It has been previously reported that while overexpression of BARD1 SVs results in cell transformation, its repression leads to growth arrest of cancer cells." (PMID 27197561, 2016). "Alternatively spliced isoforms of BARD1 have been identified in various cancers correlated with disease progression and poor prognosis." (PMID 26415510, 2015). "Differentially spliced BARD1 isoforms, in particular BARD1β, are oncogenic drivers of proliferation in cancers of various origins." (PMID 26415510, 2015). "In the present manuscript, we identified three BARD1 isoforms of potential interest as cancer markers in AML." (PMID 24349422, 2013). "However, additional genes such as BARD1, whose protein product interacts with BRCA1 via its N-terminal RING domain, have been implicated as low-penetrance contributors to cancer risk." (PMID 41301857, 2025). "Other homologous recombination DNA damage repair (HR-DDR) genes associated with other cancer risks besides breast and ovarian, such as ATM (n = 9), BARD1 (n = 4), BRIP1 (n = 2), CHEK2 (n = 5), PALB2 (n = 5), RAD51C (n = 1), and RAD51D (n = 7), accounted for an additional 4% (33/769)." (PMID 40065011, 2025). "Current NCCN surveillance management guidelines recommend only annual breast screening starting at age 40 for BARD1 mutation carriers but no surveillance management for other related cancers." (PMID 40805222, 2025). "Furthermore, while BARD1 has been ascribed multiple cellular roles, we provide additional evidence that its function in HDR is linked to cancer risk." (PMID 41282735, 2025). "In cancer cells, increased expression of OLA1 inhibits apoptosis by interacting with breast cancer-associated gene 1 (BRCA1) and BRCA1-associated RING domain protein (BARD1)." (PMID 38889130, 2024). "Additionally, USP15, recruited to DSBs by MDC1, deubiquitinates BARD1, a BRCA1 binding partner, facilitating the interaction between BARD1 and HP1γ at DSBs, thus enhancing olaparib resistance in cancer cells." (PMID 38702734, 2024). "Treatment with a PARPi in BRCA1 mutant cancers causes diminished heterodimerization with BRCA1 associated ring domain 1 (BARD1) and has been shown to decrease PAR formation and recruitment of BRCA1/BARD1 complex to the site of DNA damage." (PMID 38542143, 2024). "Moreover, cancer-associated mutations in the BRCT domains of BRCA1 and BARD1 abolish their interactions with pre-rRNA." (PMID 37789001, 2023).
cancer (continued). "In addition, BARD1 isoforms have been shown to antagonize the BRCA1-BARD1 ubiquitin ligase activity essential to induce cancer cell decease." (PMID 35650591, 2022). "Four gene markers, BARD1 (BRCA-associated RING domain 1), SOD2 (superoxide dismutase 2), S100A10, and TSC22D3 (TSC22 domain family member 3), were found to be the targets of several approved cancer drugs." (PMID 36430822, 2022). "In order to increase the control cohort, loss-of-function BARD1 variants were screened in the non-Finnish European gnomAD 2.1.1 (non-cancer) population, identifying a total of 61 heterozygous carriers out of 51,202 individuals (0.12%)." (PMID 33498765, 2021). "Autoimmune antibodies in sera of cancer patients were reactive to epitopes on BARD1 isoforms and could be exploited to develop an inverse ELISA assay for early detection of lung cancer." (PMID 34201956, 2021). "Targeting the BRCA1/BARD1 complex may provide a promising strategy for those tumors in cancer therapy." (PMID 34789768, 2021). "It has been postulated that due to altered BARD1 molecules, cancer patients generate an immune response and autoimmune antibodies against various epitopes of BARD1, which could be detected as biomarkers of cancer." (PMID 34201956, 2021). "However, several oncogenic BARD1 isoforms have been discovered in different types of cancer with antagonistic effects." (PMID 34824355, 2021). "Germline variants in the HR pathway, comprising at least 10 genes, such as BRCA1, BRCA2, ATM, BARD1, BRIP1, CHEK2, NBS1(NBN), PALB2, RAD51C, and RAD51D, lead to inherited susceptibility to specific types of cancers, including those of the breast, ovaries, prostate, and pancreas." (PMID 35008774, 2021). "BARD1 is one of the genes commonly included in the multi-cancer testing panels." (PMID 34771627, 2021). "BARD1 has been included in multi-gene panels since it was regarded as a potential cancer-predisposing gene, despite the lack of robust risk estimates." (PMID 33498765, 2021). "Importantly, RNF19A WT, but not RNF19A R1, was able to reverse the increase in HR repair caused by RNF19A deficiency and re-sensitize cells to PARPi, suggesting that the RNF19A/BARD1 interaction is essential for HR regulation and cancer cell response to PARPi." (PMID 34789768, 2021). "A novel mutation in the BARD1 gene was discovered in a patient who had 5 family members with PDAC but no other cancer types." (PMID 32708251, 2020). "However, BARD1 is also reported to be involved in BRCA1-independent oncogenic signalling modulation to facilitate cancer progression." (PMID 32719318, 2020). "Consistent with this, we found that the cancer-associated BARD1 BRCT mutants, R658C and S761N, failed to interact with p50 or stabilize it." (PMID 33024116, 2020). "Broader prospective studies and standardization (i.e., immunohistochemistry studies with BARD1-directed antibodies) will provide determination of appropriate imaging biomarkers enabling “cancer cell visibility” before they can be introduced into a clinical investigation." (PMID 33114377, 2020). "The stabilizing effect of BARD1 on p50 raised the question of whether there was an inherent correlation between these factors in human cancer." (PMID 33024116, 2020). "This study was the first report of molecular genetic analyses of BARD1 in cancer samples in 1998." (PMID 32726901, 2020). "Many studies suggest that the status of the DDR pathway affects cancer cells’ response to chemotherapy, with loss of DDR elements increasing the sensitivity to DNA-damaging platinum and PARP inhibition, such as BRCA1, BRCA2, BARD1, ATM, and PALB227." (PMID 32457312, 2020). "Overall, our results show that FL BARD1 may defend cells against cancer and prevent malignant transformation of cells." (PMID 32047556, 2020). "The importance of BARD1 in cancer development indicates how significant it is to determine whether BARD1 VUS are benign or pathogenic." (PMID 30925164, 2019).